FEN1 (flap structure-specific endonuclease 1)
Description:
Structure-specific nuclease with 5'-flap endonuclease and 5'-3' exonuclease activities involved in DNA replication and repair. During DNA replication, cleaves the 5'-overhanging flap structure that is generated by displacement synthesis when DNA polymerase encounters the 5'-end of a downstream Okazaki fragment. It enters the flap from the 5'-end and then tracks to cleave the flap base, leaving a nick for ligation. Also involved in the long patch base excision repair (LP-BER) pathway, by cleaving within the apurinic/apyrimidinic (AP) site-terminated flap. Acts as a genome stabilization factor that prevents flaps from equilibrating into structures that lead to duplications and deletions. Also possesses 5'-3' exonuclease activity on nicked or gapped double-stranded DNA, and exhibits RNase H activity. Also involved in replication and repair of rDNA and in repairing mitochondrial DNA.
Synonyms: FEN-1; MF1; RAD2
Tractability: Small molecule: a structure with a bound ligand is known; a high-quality ligand is known; it has a high-quality binding pocket; it belongs to a druggable protein family. PROTAC: ubiquitination databases record sites on it; its protein half-life has been measured; a small molecule that binds it is known.
Target class: Enzyme; Hydrolase
Gene: Protein-coding gene on chromosome 11 (61,792,725 to 61,797,238, forward strand). Ensembl gene ENSG00000168496.
Subcellular location: Nucleus, nucleolus (Isoform 1); Nucleus, nucleoplasm; Mitochondrion (Isoform FENMIT)
Subcellular location (Human Protein Atlas): Nucleoplasm; Nucleoli
Pathways (Reactome):
DNA Repair: HDR through MMEJ (alt-NHEJ); PCNA-Dependent Long Patch Base Excision Repair; POLB-Dependent Long Patch Base Excision Repair
Cell Cycle: Removal of the Flap Intermediate from the C-strand
DNA Replication: Removal of the Flap Intermediate
Disease: Early Phase of HIV Life Cycle
Gene Ontology:
Molecular function: 5'-3' exonuclease activity; 5'-flap endonuclease activity; DNA binding; flap endonuclease activity; protein binding; RNA-DNA hybrid ribonuclease activity; damaged DNA binding; double-stranded DNA binding; double-stranded DNA exodeoxyribonuclease activity; endonuclease activity; exonuclease activity; magnesium ion binding; manganese ion binding; catalytic activity; DNA endonuclease activity; hydrolase activity, acting on ester bonds; nuclease activity
Biological process: DNA replication, removal of RNA primer; positive regulation of sister chromatid cohesion; base-excision repair, gap-filling; DNA repair; DNA replication; double-strand break repair; double-strand break repair via homologous recombination; telomere maintenance via semi-conservative replication; UV protection; base-excision repair; DNA recombination; memory
Cellular component: chromosome, telomeric region; membrane; mitochondrion; nucleolus; nucleoplasm; nucleus; protein-containing complex
Genetic constraint (gnomAD): Loss-of-function variants: 19 observed, 26.02 expected, observed/expected ratio (o/e) 0.73, 90% interval 0.51 to 1.07. The synonymous counts are far from expectation, so gnomAD's model fits this gene poorly and the ratio says little. Missense variants: 339 observed, 507.16 expected, observed/expected ratio (o/e) 0.67, 90% interval 0.61 to 0.73. Synonymous variants: 155 observed, 198.4 expected, observed/expected ratio (o/e) 0.78, 90% interval 0.69 to 0.89.
Homologues: Orthologues: chimpanzee FEN1 (100% identical), macaque FEN1 (99% identical), dog FEN1 (98% identical), rabbit FEN1 (98% identical), pig FEN1 (97% identical), mouse Fen1 (97% identical), rat Fen1 (96% identical), guinea pig FEN1 (94% identical), tropical clawed frog fen1 (81% identical), zebrafish fen1 (77% identical), Drosophila melanogaster Fen1 (64% identical), Caenorhabditis elegans crn-1 (62% identical). Paralogues in human: GEN1 (23% identical), EXO1 (22% identical).
Diseases named in the same sentence as FEN1 in open-access papers:
FEN1 is named in the same sentence as 117 diseases in open-access papers, as found by Europe PMC text mining. Sharing a sentence is not in itself a finding about the gene and the disease. The quoted sentences say what the papers report.
breast carcinoma (61 papers, 2008 to 2025). "The FEN1-69GG genotypes were also found to be significantly correlated with an increased risk of developing breast cancer, which defined FEN1 as an important gene in human breast carcinogenesis." (PMID 40685548, 2025). "Base excision repair proteins including XRCC1, APE1, SMUG1, and FEN1 were significantly associated with poor breast-cancer-specific survival." (PMID 39199284, 2024). "It was shown that Curcumin plus Cisplatin increased the susceptibility of breast cancer cells to cisplatin through downregulating FEN1 expression both in vivo and in vitro." (PMID 39453820, 2024). "Polymorphisms ERCC3/XPB, NEIL-2, NTH-1, and FEN-1 have been studied in lung, gastric, lung, and breast cancer." (PMID 38892180, 2024). "Curcumin reduces the overexpression of flap endonuclease 1 (FEN1), an enzyme associated with cisplatin-resistance in breast cancer cells, thereby increasing the sensitivity of cancer cells to this chemotherapeutic agent." (PMID 37176840, 2023). "FEN1 overexpression has been shown to be associated with aggressive behavior and poor survival in different tumors, including breast cancer, ovarian cancer, and non-small cell lung cancer." (PMID 37993428, 2023). "This study aims to identify the potential value of flap endonuclease 1 (FEN1) as a diagnostic and prognostic marker for breast cancer (BC)." (PMID 34277392, 2021). "Previous studies have demonstrated that FEN1 single-nucleotide polymorphisms (SNPs) are involved in various cancer developments, including breast cancer, lung cancer, hepatocellular carcinoma, esophageal cancer, and gastric cancer as well as glioma." (PMID 32399086, 2020). "This was a new discovery following the association of FEN1 with drug resistance to breast cancer, lung cancer, cervical cancer and osteosarcoma." (PMID 32586310, 2020). "We depicted a schematic diagram illustrating how FEN1 overexpression is associated with cisplatin resistance and the chemosensitizing effect of curcumin in breast cancer cells." (PMID 29541412, 2018). "It was found that the FEN1‐69GG genotypes were significantly correlated with increased risk for developing breast cancer, which highlights FEN1 as an important gene in human breast carcinogenesis." (PMID 28371273, 2017). "This study aimed to assess the associations of two common Flap endonuclease 1 (FEN1) polymorphisms (rs4246215 and rs174538) with breast cancer risk in northwest Chinese women." (PMID 27801669, 2016). "Key base excision repair (BER) proteins, including XRCC1, APE1, SMUG1, and FEN1, were independently associated with poor breast cancer-specific survival (BCSS) (ps≤0.01)." (PMID 25111287, 2014). "Low XRCC1 (p<0.01), low APE1 (p<0.01), low SMUG1 (p<0.01), and high FEN1 (p<0.01) remain independently associated with poor breast cancer-specific survival (BCSS)." (PMID 25111287, 2014). "For example, L1CAM, GATA4, CCNB1, CDKN1C, and FEN1 have been reported for their association with breast cancer: L1CAM was shown to inhibit the growth of breast carcinoma cells." (PMID 18237428, 2008). "Of great relevance for understanding the effects of an inhibitor was the investigation of whether the target protein FEN1 is evenly present and distributed in all cell lines and if the underlying FEN1 gene expression is increased in breast cancer." (PMID 38396787, 2024). "FEN1 might be a therapeutic target due to its function at the cellular level, its elevated gene expression in breast cancer, and its association with drug resistance." (PMID 38396787, 2024). "FEN1 might represent both a possible diagnostic tool in form of a biomarker and a potential target molecule for a novel personalized therapy in breast cancer." (PMID 38396787, 2024). "This could also be due to mutations in the FEN1 gene, as it is well known that breast cancer genetic subtypes are very heterogenous." (PMID 38396787, 2024). "FEN1 overexpression can also cause resistance to many chemotherapeutic drugs in breast cancer." (PMID 29541412, 2018).
breast carcinoma (continued). "Curcumin-treated breast cancer cells showed a significant decrease in cell proliferation, mediated by Nrf-2 nuclear translocation, associated with the down-regulation of Flap endonuclease 1 (Fen1), which is a nuclease involved in DNA repair." (PMID 27657126, 2016). "We searched PubMed, the ISI Web of Knowledge, Embase and China National Knowledge Infrastructure about the genome-wide association study of FEN1, only find one study in east China (Huaian, Jiangsu Province and Jinan, Shandong Province) about the association between the FEN1 and breast cancer risk." (PMID 27801669, 2016). "Moreover, Breast Cancer Gene Expression Miner v4.2 (bc-GenExMiner v4.2) data demonstrate that high FEN1 was significantly associated with increased probability of distant metastasis and shorter overall survival (p < 0.001, HR = 1.64, 95% CI = 1.50–1.81) (c respectively)." (PMID 34117958, 2021). "Our results suggest that FEN1 polymorphisms may reduce the risk of breast cancer in Chinese women." (PMID 27801669, 2016). "In breast cancer, overexpression of YY1 has been associated with decreased Flap Endonuclease 1 (FEN1) expression and increased sensitivity to chemotherapy drugs such as mitomycin C and Taxol." (PMID 41327312, 2025). "This biosensor is able to detect endogenous FEN1 activity in a single cell, and even distinguish the FEN1 level in healthy paracancerous tissues and breast cancer tissues." (PMID 39589999, 2024). "The impact of FEN1-IN-4 is examined on eight breast cancer cells, breast epithelial cells, and healthy skin fibroblasts." (PMID 38396787, 2024). "The effect of FEN1-IN-4 on breast cancer cells, including TNBC, can be achieved both with monotherapy and in combination with IR." (PMID 38396787, 2024). "Studies showed that FEN1 expression is increased 2.5-fold in breast cancer tissue and the FEN1 expression is even higher in metastatic tissue than in the associated tumor." (PMID 38396787, 2024). "It is revealed that overexpression of Flap endonuclease 1 (FEN1) has an important role in development of breast cancer." (PMID 39453820, 2024). "Linear regression analyses were performed on the breast cancer cell lines to link the results of the experimental modalities with the previously basic FEN1 quantity." (PMID 38396787, 2024). "Inhibition the proliferation of breast cancer cells by Nrf2-mediated down-regulation of Fen1 expression." (PMID 37191432, 2023). "Curcumin is capable of suppressing the proliferation of breast cancer cells via Nrf2-mediated reduction of Fen1 activation." (PMID 37191432, 2023). "The miR-140 was reported to act as a tumor suppressor by targeting the FEN1 gene which leads to repressing the DNA damage repair in breast cancer cells." (PMID 36980610, 2023). "Inhibition of FEN1 decreases ERα activity and proliferation in breast cancer cells resistant to tamoxifen, suggesting the therapeutic potential of FEN1 as a target molecule in endocrine therapy resistance." (PMID 35498431, 2022). "Clinical data analysis also found that miR-140 expression was down-regulated when FEN1 expression was up-regulated in breast cancer tissues." (PMID 35883563, 2022). "Activation of FEN1 in tamoxifamine-resistant breast cancer regulates ERα activity by stabilizing chromatin interactions." (PMID 35883563, 2022). "MiR-140 inhibited the expression of FEN1 by directly binding to its 3′ untranslated region, resulting in blocked DNA repair and thus hindering the progression of breast cancer." (PMID 35883563, 2022). "One example of those proteins is the endonuclease FEN1, which is increased in tamoxifen-treated breast cancer patients, promoting the transcriptional activity of ERα." (PMID 35498431, 2022). "Our previous study found that miR-140 inhibits Flap endonuclease 1 (FEN1) expression via directly binding to its 3′ untranslated region, leading to impaired DNA repair and inhibition of breast cancer progression." (PMID 36439421, 2022).
breast carcinoma (continued). "FEN1 is highly expressed in a variety of tumors, including prostate cancer, neuroblastoma, pancreatic and breast cancer, lung cancer, testicular cancer, glioblastoma, and astrocytoma and so on." (PMID 35883563, 2022). "An increasing number of studies have suggested that FEN1 plays an extremely important role in the pathogenesis in multiple cancers, including breast cancer, NSCLC, and gastric cancer." (PMID 35246224, 2022). "As reported in breast cancer, FEN1 is related to the resistance of trastuzumab, tamoxifen, temozolomide, fluorouracil, cisplatin and other chemotherapeutics drugs." (PMID 33827468, 2021). "Curcumin also inhibited the proliferation of MCF-7 breast cancer cells through Nrf2-mediated down-regulation of DNA repair-specific nuclease, Flap endonuclease 1 (Fen1)expression by reducing the Nrf2 recruitment to the Fen1 promoter." (PMID 35126099, 2021). "Curcumin was found to enhance the sensitivity of breast cancer cells to cisplatin by downregulating FEN1 expression in vitro." (PMID 34572272, 2021). "Using WB, FEN1 overexpression has been demonstrated in breast cancer cell lines MDA-MB-231, MCF7, and MDA-MB-435 when compared with the healthy breast cell line MCF10A." (PMID 34809722, 2021). "Up-regulated expression of FEN1 is reported in various malignant tumor cells, including breast cancer, lung cancer, gastrointestinal tumors, hepatocellular carcinoma and cervical cancer." (PMID 33827468, 2021). "FEN1 overexpression increases breast cancer progression and its transcription is also activated following anti-cancer treatments." (PMID 33662042, 2021). "For example, Flap endonuclease 1 (FEN1) overexpression in breast cancer cell lines promotes resistance to the chemotherapeutic agent cisplatin." (PMID 34572272, 2021). "Our data shows that AEs/PTX reduced cell proliferation by increasing DNA damage response (DDR) mediated by Flap endonuclease 1 (FEN1) downregulation that results into enhanced breast cancer cell sensitivity to chemotherapeutic drugs." (PMID 31998443, 2020). "Together with quinacrine, curcumin binds DNA more efficiently, being able to cause further damage to breast cancer stem cells and preventing their repair by lowering the expression of DDB2, Polβ, Polδ, PolH, Rad51, Fen1, XRCC1, CHK1, and RPA proteins." (PMID 33330091, 2020). "Previous studies have reported that overexpression of FEN1 is positively correlated with poor prognosis of non-small-cell lung cancer and breast cancer, as well as lung adenocarcinoma." (PMID 32399086, 2020). "Recently, FEN1 expression was found to be a predictive marker for resistance to tamoxifen in ERα-positive breast cancers, and that a novel FEN1 inhibitor (FENi#2) reduced breast cancer cell proliferation in vitro, even in tamoxifen resistant cell lines." (PMID 32648895, 2020). "In curcumin-treated MCF-7 breast cancer cells, a decrease in FEN1 (long patch BER pathway) was observed as a result of overexpression of NRF2 and its positioning on the promoter of this gene, thus collaborating to prevent cell proliferation." (PMID 33330091, 2020). "Another study demonstrated that FEN1 promoted breast cancer cell proliferation via an epigenetic mechanism whereby FEN1-mediated up-regulation of DNMT1 and DNMT3a." (PMID 31534853, 2019). "The transcriptional repressive function of YY1 was further shown to result in suppression of breast cancer growth by direct repression of FEN1 gene and indirect repression of FEN1 through inducing miR-140 expression, which was shown to target FEN1 3′UTR." (PMID 31824839, 2019). "Our previous studies have shown that FEN1 down-regulation expression can effectively inhibit the proliferation of breast cancer cells overexpressing FEN1." (PMID 29541412, 2018). "We also demonstrated that curcumin sensitizes breast cancer cells to cisplatin through FEN1 down-regulation." (PMID 29541412, 2018).
breast carcinoma (continued). "Increased ERK phosphorylation contributed to cisplatin resistance and cisplatin-induced FEN1 overexpression in breast cancer cells." (PMID 29541412, 2018). "In breast cancer and prostate cancer, the overexpression of FEN1 is characterized as a possible biomarker for monitoring the progression of cancers and a potential target for therapy." (PMID 29541412, 2018). "Curcumin can enhance breast cancer cell sensitivity to cisplatin by down-regulating FEN1 expression, which is accomplished by decreasing curcumin-induced ERK phosphorylation." (PMID 29541412, 2018). "After the breast cancer cells were subjected to a treatment with a combination of curcumin with cisplatin, both cisplatin sensitivity and FEN1 expression were decreased compared with cells treated with cisplatin alone." (PMID 29541412, 2018). "We demonstrated that FEN1 overexpression promotes cisplatin resistance in breast cancer cells, and that FEN1 knockdown enhances cisplatin sensitivity." (PMID 29541412, 2018). "We investigated the role of FEN1 in cisplatin resistance and the chemosensitizing effects of curcumin in breast cancer cells." (PMID 29541412, 2018). "This suggests that the chemosensitizing effect of curcumin to cisplatin in breast cancer cells is achieved through FEN1 down-regulation." (PMID 29541412, 2018). "A combination of cisplatin and curcumin enhanced breast cancer cell sensitivity to cisplatin by down-regulating FEN1 expression in vitro and in vivo." (PMID 29541412, 2018). "Our previous study demonstrated that curcumin inhibits cell proliferation through the down-regulation of FEN1 expression in breast cancer cells." (PMID 29541412, 2018). "It is a DNA repair-specific nuclease and over-expression of FEN1 is involved in breast cancer development." (PMID 28724427, 2017). "It was lack of repeated research to verifying the relationship between these two common SNPs of FEN1 and breast cancer." (PMID 27801669, 2016). "Using cancer profiling array and immune-histochemistry, we have previously found that FEN1 is clearly over-expressed in breast cancer tissues." (PMID 25885449, 2015). "Reduction of YY1 levels in breast cancer cells results in overexpression of FEN1 leading to resistance to chemotherapeutic drugs." (PMID 25885449, 2015). "Seeking the relevance between FEN1 expression and cancer patient outcomes, we performed survival analysis using 5 different breast cancer patient cohorts, namely Ivshina, Huang, Pawitan, Sotiriou, and Wang, all of which are available in the literature." (PMID 25885449, 2015). "Further seeking the association between FEN1 and YY1 expression levels and survivorship in breast cancer patients, we studied a cohort that made available in the First Hospital of China Medical University." (PMID 25885449, 2015). "Over-expression of Flap endonuclease 1 (Fen1), a DNA repair-specific nuclease, is involved in the development of breast cancer." (PMID 25665066, 2015). "The fact that FEN1 expression was high in breast cancer cell lines was consistent with our published data." (PMID 25885449, 2015). "From the clinical standpoint, FEN1 is a good candidate biomarker for prognostics of breast cancer patients based on evidences that we made available in the current studies." (PMID 25885449, 2015). "FEN1 is up-regulated in human breast cancer and its levels inversely correlated with cancer drug and radiation resistance and with survivorship in breast cancer patients." (PMID 25885449, 2015). "In addition, the elevated expression of flap endonuclease 1 (FEN1) correlates with drug resistance and patient survival in breast cancer." (PMID 40867514, 2025). "Other miRNAs, such as miR-140 and miR-193b, have been shown to regulate FEN1 in breast cancer and osteosarcoma, although their specific role in modulating FEN1’s DNA repair functions in OvCa remains unknown." (PMID 41008855, 2025).